ATP2B4 (ATPase plasma membrane Ca2+ transporting 4)
Diseases named in the same sentence as ATP2B4 in open-access papers (continued):
Sharing a sentence is not in itself a finding about the gene and the disease.
tumor (17 papers, 2006 to 2025). "ATP2B4 plays a role in cellular calcium homeostasis that may be altered in tumor cells in parallel to the loss of ion transporters seen at the gene level." (PMID 17192196, 2006). "Nonetheless, among MCs we identified one tumor harboring a GNAQ p.Q209L mutation and one case with an ATP2B4/PRKCA fusion." (PMID 41324772, 2025). "Six overlapping AS events regulated by SF3B4 in tumor samples were finally verified, including 1 SE event (ATP2B4) and 5 RI events in 4 genes (SRSF5, PHF6, SNHG12, KIAA1217)." (PMID 33563334, 2021). "Although the expression of Atp2b4, also considered to be a housekeeping isoform, shows a level several orders of magnitude smaller, an increased level of this isoform is again found in tumor cells." (PMID 34737944, 2021). "The expression of a particular isoform, PMCA4b (ATP2B4), is downregulated in cancer cells from various tumor types, and hence suggested to play a key role during malignant transformation." (PMID 32414111, 2020). "Gene chip microarray data showed that ATP2B4 was predominantly over-expressed (2.65-fold, n = 39, p < 4.06−10) to a much greater extent than ATP2B1 (1.24-fold, n = 39, p < 0.035) in human PDAC tumors versus resected healthy tissue from the tumor margin." (PMID 31963119, 2020).
cancer (15 papers, 2011 to 2025). A tumor composed of atypical neoplastic, often pleomorphic cells that invade other tissues. "Through ENCORI database with the specific condition (strict stringency; 10 cancer types), three possible mRNAs were observed to be shared by miR-362-5p and miR-500b-5p, which were RNF145, SAMD4A (sterile alpha motif domain containing 4A) and ATP2B4 (ATPase plasma membrane Ca2+ transporting 4)." (PMID 35365168, 2022).
infection (6 papers, 2014 to 2024). The state of being infected such as from the introduction of a foreign agent such as serum, vaccine, antigenic substance or organism. "When compared to productive infection with HIV-1YU2, the proviruses in ATP2B4 and ZNF486 were expressed at >100 and >27,000-fold lower levels respectively." (PMID 38746186, 2024).
ATP2B4 also shares sentences with these, for which no sentence is quoted: male infertility (6 papers); Hypertension (4); infertile (4); pancreatic ductal adenocarcinoma (4); colorectal cancer (3); gastric cancer (3); myocardial infarction (3); adenoma (2); anemia (2); asthenozoospermia (2); bladder cancer (2); cutaneous melanoma (2); heart failure (2); pancreatitis (2); parasitemia (2); prostate carcinoma (2); Spastic paraplegia (2); X-linked cerebellar ataxia (2); acute kidney injury (1); Alzheimer disease (1); Arrhythmia (1); choroidal melanoma (1); colorectal tumor (1); conjunctival melanoma (1); developmental dysplasia of the hip (1); ductal carcinoma in situ (1); dysplastic nevus (1); endometrial cancer (1); G6PD deficiency (1); glioma (1).
A further 20 diseases each share a sentence with ATP2B4 in 1 paper.